CRP (C-reactive protein)
Diseases named in the same sentence as CRP in open-access papers (continued):
Sharing a sentence is not in itself a finding about the gene and the disease.
hepatocellular carcinoma (113 papers, 2009 to 2026). A malignant tumor that arises from hepatocytes. "Existing research has identified an association between C-reactive protein and the occurrence of hepatocellular carcinoma, with higher C-reactive protein levels correlating with increased risk of liver cancer." (PMID 41602421, 2026). "In conclusion, ultrasonography combined with AFP, SAA, and CRP significantly improves early detection of hepatocellular carcinoma in high-risk populations." (PMID 40660552, 2025). "Systemic inflammatory response represented by C-reactive protein to albumin ratio (CAR) was shown to be associated with long-term outcome in patients with hepatocellular carcinoma (HCC)." (PMID 39410928, 2024). "The study found that higher concentrations of CRP were positively associated with an elevated risk of hepatocellular cancer." (PMID 33256656, 2020). "Recent studies have indicated that the C-reactive protein/ albumin (CRP/Alb) ratio is associated with clinical outcomes in patients with hepatocellular carcinoma (HCC)." (PMID 26084991, 2015). "IL-6 is the main inducer of CRP production in vitro in cultured human hepatoma cells, but data about the associations of IL-6 and CRP in vivo is scarce." (PMID 20500875, 2010). "Meanwhile, CRP associated with systemic inflammatory processes has been shown to be a prognostic and predictive marker in various solid tumors, including renal, gastrointestinal, and hepatocellular carcinoma." (PMID 33201589, 2020). "Elevated CRP is noted in and associated with aggressive hepatocellular carcinoma." (PMID 33324413, 2020). "Because the normal limit of CRP ranges from 0 to 5 mg/L in our institution and a study of hepatocellular carcinoma applied 5 mg/L as a threshold for the best sensitivity, specificity, and diagnostic accuracy 14, we used 5 mg/L as the cut‐off value for CRP in this study." (PMID 26799163, 2016). "Soluble PD-1 levels association with systemic inflammation markers (CRP), active disease, hepatitis B viral load, HCC (Hepatocellular carcinoma) risk, and worst prognostic factors in DLBCL (Diffuse large B-cell lymphoma) is indicative of its predictive value." (PMID 33329567, 2020). "This aligns with the pathway demonstrated in this study’s model, wherein serum total calcium influences C-reactive protein, which in turn affects hepatocellular carcinoma development." (PMID 41602421, 2026). "Child-Pugh classes, Model for End-Stage Liver Disease score, presence of hepatocellular carcinoma and laboratory variables including SA, D-dimer, and high-sensitivity C-reactive protein (hs-CRP) were measured at baseline." (PMID 39165413, 2024). "This is consistent with published findings on hepatocellular carcinoma that indicates poor clinical outcomes in patients with high levels of serum acute phase proteins including CRP who are treated with PD-1 inhibitors." (PMID 38304429, 2024). "Maximum CRP expression is seen in cells treated with both IL-6 and IL-1 in human hepatoma Hep3B cells." (PMID 37860004, 2023). "IGF-1 has an anti-inflammatory effect in human hepatoma cell lines, reducing c-reactive protein (CRP) and fibrinogen mRNA transcripts." (PMID 37520312, 2023). "CRP synthesis, on the other hand, was shown to be mainly regulated by IL-6 in the hepatoma cell lines." (PMID 35883605, 2022). "Like PAI-1, the cytokine-driven production of SAA and CRP in hepatoma cell-lines can be potentiated by GCs." (PMID 35883605, 2022). "In other cancer types, serum CRP was proposed as a predictive marker of the treatment response of checkpoint inhibitors in hepatocellular carcinoma and melanoma." (PMID 36428750, 2022). "We investigated the impact of C-reactive protein to albumin ratio (CAR) on predicting outcomes in 522 patients with unresectable hepatocellular carcinoma (HCC) treated with lenvatinib." (PMID 35589772, 2022).
hepatocellular carcinoma (continued). "The novel CRP–albumin–lymphocyte (CALLY) index has been identified as a highly predictive tool for stratification of patients with hepatocellular carcinoma (HCC) who have undergone tumor resection." (PMID 34638502, 2021). "Previous studies revealed that an increased clustering coefficient correlated with bloodstream C-reactive protein concentration or inflammation in hepatocellular carcinoma patients before and after transarterial chemoembolization." (PMID 33667236, 2021). "C-reactive protein (CRP) is a widely used marker of systemic inflammation and predicts poor clinical outcomes in patients with hepatocellular carcinoma (HCC); however, its significance in the local immune response at the tumor site is not clear." (PMID 35070979, 2021). "For hepatocellular carcinoma research, 52 proteins were identified to interact with C reactive protein by iTRAQ-based proteomic profiling, contributing to the understanding of molecular pathogenesis of hepatocellular carcinoma." (PMID 33407071, 2021). "Recently, the CRP/Alb ratio has been reported to be a prognostic predictor in patients with hepatocellular carcinoma and patients with UICC stage III or IV PDAC with a cut-off value of 0.54." (PMID 30974894, 2019). "Our results show that gemcabene inhibited cytokine-stimulated CRP production in human hepatoma cells at doses consistent with clinical exposures." (PMID 29644527, 2018). "First, we evaluated gemcabene-induced regulation of CRP production in human hepatoma cells and anti-inflammatory activity in human coronary aortic endothelial cells, both important in the regulation of genes that influence progression of CVD." (PMID 29644527, 2018). "In human hepatoma cells, gemcabene inhibited IL-6 plus IL-1β-induced CRP production in a concentration-dependent manner, reaching 70% inhibition at 2 mM." (PMID 29644527, 2018). "We therefore used these cytokines to induce CRP promoter activity to study gemcabene-mediated inhibition in Alexander hepatoma and endothelial cell lines." (PMID 29644527, 2018). "Since CRP is produced mainly in the liver in response to interleukin-6 (IL-6), we evaluated the effect of gemcabene on CRP production by cytokine-stimulated human hepatoma PLC/PRF/5 (Alexander) cells." (PMID 29644527, 2018). "In the current study, we show that the CRP promoter is up-regulated by IL-6/ IL-1β or with IL-6 alone in a human hepatoma cell line." (PMID 29644527, 2018). "And one study from Japan showed that the patients with elevated CRP had larger tumor size in hepatocellular carcinoma." (PMID 27303917, 2016). "Regarding the effects of TAGE on hepatocytes, we recently reported that TAGE-RAGE interactions stimulated hepatic C-reactive protein (CRP) in human hepatoma Hep3B cells via the activation of Rac-1." (PMID 27338481, 2016). "A more recent study has found that C-reactive protein, at the time of diagnosis, predicts poorer outcomes in hepatocellular carcinoma patients that are unable to have tumor removal surgeries." (PMID 27733196, 2016). "In other solid tumors (lung, pancreas, hepatocellular cancer, and bladder) an elevated CRP also predicted prognosis." (PMID 26717416, 2015). "Recently, the CRP/Albumin (CRP/Alb) ratio was reported to correlate with poor prognosis in patients with hepatocellular carcinoma." (PMID 26390126, 2015). "We previously reported the usefulness of CRP in predicting short-term mortality in patients with hepatocellular carcinoma (HCC), and outcomes after liver transplantation." (PMID 26498833, 2015). "Gender, hepatitis B, TC, and AT3 constitute risk factors for hepatocellular carcinoma in cirrhotic patients; Gender, hepatitis type, DOI, FT4, AT3, SCC, CRP, MAO, and Ca are associated with the progression of liver cirrhosis to malignant liver tumours either directly or indirectly." (PMID 41602421, 2026).
hepatocellular carcinoma (continued). "In a multicenter retrospective analysis, CRP and alpha-fetoprotein were found to score immunotherapy in patients with hepatocellular carcinoma treated with atezolizumab in combination with bevacizumab, and patients with AFP ≥ 100 ng/mL and CRP ≥1 mg/dL were found to have a poorer prognosis." (PMID 39741972, 2024). "Also, increased amounts of inflammatory mediators such as TNF-α, C-reactive protein, and IL-6 have been found in the sera of hepatocellular carcinoma patients." (PMID 36430792, 2022). "However, several in vitro studies investigating SAA and CRP mRNA and protein expression in hepatoma cell lines, show differential regulation by these cytokines." (PMID 35883605, 2022). "Because not only normal hepatocytes but also hepatoma cells can produce serum CRP, it could be regarded that elevated CRP is related to hepatic tumor burden, and this has supporting evidence." (PMID 23409924, 2013). "In summary, gender, hepatitis type, disease duration, total calcium, C-reactive protein, total cholesterol, antithrombin III activity, free thyroxine, and carcinoembryonic antigen are closely associated with the progression of liver cirrhosis to hepatocellular carcinoma." (PMID 41602421, 2026). "Levels of C-reactive protein (CRP) and alpha-fetoprotein (AFP) in immunotherapy (CRAFITY) scores are associated with the prognosis of patients with hepatocellular carcinoma (HCC)." (PMID 39555053, 2024). "In addition, CRP level seems to reflect mechanism of hepatocellular cancer development." (PMID 36923698, 2023). "However, the clinicopathological significance of CRP levels in hepatocellular carcinoma (HCC) patients being treated with PD-1 inhibitors remains unclear." (PMID 35185894, 2022). "CRP plays an important role in the development and/or prognosis of a variety of cancers, including esophageal cancer, hepatocellular carcinoma (HCC), and non-small cell lung cancer." (PMID 34001040, 2021). "In further research on the CRP/Alb ratio for predicting the overall survival of patients with cancer, available research indicated that the CRP/Alb ratio was an efficacious prognostic factor in hepatocellular carcinoma, esophageal squamous cell carcinoma and NPC." (PMID 27854304, 2016). "In patients with hepatocellular carcinoma (HCC), these systemic inflammatory responses can be detected by routine laboratory tests, such as levels of C-reactive protein (CRP) and the neutrophil-lymphocyte ratio (NLR)." (PMID 27733127, 2016). "This meta-analysis aimed to assess the performance of the CRAFITY (CRP and AFP in immunotherapy) score as a prognostic factor in hepatocellular carcinoma (HCC) treated with immunotherapy." (PMID 36915049, 2023). "For instance, multivariate analysis indicated that C-reactive protein (CRP) and serum alpha-fetoprotein (AFP) at baseline were independent predictors of the prognosis of PD-L1-based therapy in hepatocellular carcinoma (HCC)." (PMID 37268978, 2023). "In the past few years, CRP, GPS, and CAR have been shown to have prognostic value in patients with hepatocellular carcinoma and gallbladder, pancreatic, ovarian, esophageal, and gastric cancers." (PMID 34765598, 2021). "The aim of this study was to propose a prognostic scoring system based on preoperative serum apolipoprotein A-1 and C-reactive protein (ApoA-1 and CRP, AC score) levels and to evaluate the prognostic value of these markers in patients with hepatocellular carcinoma (HCC)." (PMID 30486825, 2018). "The C-reactive protein albumin (CRP/Alb) ratio, a novel inflammation-based prognostic score, has been demonstrated to show outstanding prognostic value in hepatocellular carcinoma compared with other established inflammation-based prognostic scores." (PMID 25934640, 2015). "Treatment of human hepatocellular carcinoma cells was shown to induce CRP expression, which was dependent on STAT3 binding sites within the CRP promoter." (PMID 24743777, 2014).
hepatocellular carcinoma (continued). "In Shasha Shen's study, CRP expression was upregulated in hepatocellular carcinoma (HCC) tissues compared with that in noncancerous tissues." (PMID 33201589, 2020). "Therefore, an inflammation-based index using serum c-reactive protein (CRP) and albumin values was shown to correlate with survival in patients with hepatocellular carcinoma undergoing stereotactic body radiotherapy." (PMID 30737542, 2019). "We did not detect CRP expression in TETs, although CRP expression has been already demonstrated in other solid tumors, including hepatocellular carcinoma, esophageal cancer or renal cell cancer." (PMID 28514756, 2017). "The prognostic significance of the CRAFITY score (CRP and AFP in ImmunoTherapY) has been demonstrated in hepatocellular carcinoma (HCC) patients receiving immunotherapy." (PMID 38365678, 2024). "CRP and albumin may be active mediators of both hepatocellular cancer development and a more aggressive phenotype, rather than merely passive reflections of inflammatory processes." (PMID 36923698, 2023). "CRP and albumin ratio (CAR), as a new inflammation-based prognostic score, has been demonstrated to show prognostic value in hepatocellular carcinoma (HCC), oesophageal squamous-cell carcinoma, and small-cell lung cancer." (PMID 34726101, 2021). "Recent studies have suggested that CRP can serve as a surrogate biomarker for acute or chronic systemic inflammation, which may be poorly predicted by the MELD score in patients with ESLD, such as alcoholic hepatitis, hepatocellular carcinoma, tissue necrosis, and bacterial translocation." (PMID 31821367, 2019). "Several markers of systemic inflammation, including blood C-reactive protein, platelet lymphocyte ratio (PLR) and neutrophil lymphocyte ratio (NLR) have been identified as independent prognosticators for hepatocellular carcinoma (HCC)." (PMID 30662766, 2019). "We aimed to elucidate whether CRP and NLR could serve as potential surrogate markers for response and survival in patients with hepatocellular carcinoma (HCC)." (PMID 23409924, 2013). "Serum C-reactive protein (CRP) is a prognostic factor for overall survival (OS) and recurrence of hepatocellular carcinoma (HCC) in patients treated with resection or non-surgical treatment." (PMID 31141535, 2019). "The lymphocyte-C-reactive protein ratio (LCR) is a recently described inflammation-based score, and it remains unclear which is the optimal inflammation-based score among patients with hepatocellular carcinoma (HCC) who underwent transarterial chemoembolization (TACE)." (PMID 33589570, 2021).
Alzheimer disease (112 papers, 2010 to 2026). A progressive, neurodegenerative disease characterized by loss of function and death of nerve cells in several areas of the brain leading to loss of cognitive function such as memory and language. "In Alzheimer's disease, senile plaque formation is an acute phase inflammatory state which is associated with high CRP levels." (PMID 36381804, 2022). "It is proven that decreased levels of CRP are linked with rapid functional and cognitive deterioration, whereas raised CRP levels indicate more risk of Alzheimer's disease development." (PMID 36381804, 2022). "In our clinical practice, serum CRP levels have diagnostic value for mild and moderate Alzheimer's disease, as its levels are decreased among patients with a mild and moderate form of the disease." (PMID 36381804, 2022). "We observed that the genetic signal for both hip fractures (the present study) and Alzheimer’s disease, rs429358, was also robustly associated with C-reactive protein levels and serum cholesterol levels." (PMID 36260985, 2022). "CRP levels are also associated with degenerative disorders of the nervous system like Alzheimer’s disease." (PMID 36381804, 2022). "Pro-inflammatory cytokines like IL-6, TNFα, and C-reactive protein (CRP) have been associated with pathological conditions like Alzheimer’s disease, and cardiovascular diseases." (PMID 36369012, 2022). "Although the underlying mechanism is not fully understood, it has been reported that high inflammation (high CRP) is associated with increased risk of Alzheimer's disease among e4 genotypes (e3e4 or e4e4) but less so among non‐e4 genotypes." (PMID 34038024, 2021). "In this population-based cohort study, chronic low-grade inflammation, assessed by longitudinal C-reactive protein measurements, was associated with an increased risk of Alzheimer disease only in ApoE4 carriers." (PMID 30646251, 2018). "C-reactive protein (CRP), a blood inflammatory biomarker, is associated with the development of Alzheimer disease." (PMID 26308525, 2015). "The APOE locus is also strongly associated with neurological disease (particularly Alzheimer’s disease), cardiac, metabolic, and vascular diseases, plasma C-reactive protein levels, and, in a recent study, nonpathological cognitive aging." (PMID 26077337, 2015). "Alzheimer’s disease is also closely associated with low-grade chronic inflammation as highlighted by a number of increased systemic inflammation markers including C-reactive protein (CRP), fibrinogen, interleukin-6 (IL-6), and tumor necrosis factor α (TNF-α)." (PMID 25225492, 2014). "Of note, observational and genetic evidence has supported an association of low CRP levels with increased risk of Alzheimer’s disease, and further work is required to delineate the dose–response relationship between IL-6 signaling mediated changes in CRP levels and potential adverse outcomes." (PMID 35948913, 2022). "Sleep quality improvements are associated with reductions in inflammatory markers associated with Alzheimer disease, that is, C-reactive protein (small effects) and interleukin-6 concentrations (large effects), as well as expression of inflammatory-related genes." (PMID 35700020, 2022). "Epidemiological studies have consistently shown that elevated levels of the inflammatory biomarker C-Reactive Protein (CRP) are associated with an increase in risk for developing cardiovascular disease, autoimmune and metabolic diseases, Alzheimer’s disease, and cancer." (PMID 31295270, 2019). "CRP is an important upstream mediator of inflammation and is associated with the onset of a number of important disease states including cardiovascular disease and neurodegenerative disorders such as Alzheimer’s disease." (PMID 29892284, 2018). "Furthermore, some chronic inflammatory diseases such as hemorrhagic stroke, Alzheimer’s disease (AD), and Parkinson’s disease (PD) are also associated with CRP formation." (PMID 29951057, 2018).